BRAF (B-Raf proto-oncogene, serine/threonine kinase)
Diseases named in the same sentence as BRAF in open-access papers (continued):
Sharing a sentence is not in itself a finding about the gene and the disease.
lung carcinoma (continued). "For lung cancer, we collect the status of the National Comprehensive Cancer Network (NCCN) recommended biomarkers: EGFR, ALK, BRAF, ROS1, KRAS, RET, NTRK and PD-L1." (PMID 33572220, 2021). "Especially in lung cancer, various targeted therapies have been developed, ranging from EGFR-TKIs and BRAF, ALK, ROS, RET, MET, TRK1, and HER2 inhibitors, to more recent developments in KRAS inhibitors." (PMID 34359729, 2021). "HER2 mutations mainly occur at exon 20 in the protein kinase domain and are recognized as primary drivers in lung cancer, similar to other oncogenic drivers, such as EGFR, ROS, ALK, KRAS and BRAF." (PMID 33959501, 2021). "Pulmonary LELC had better prognosis, and previous studies also have discovered that classic lung cancer oncogenic drivers including KRAS, EGFR, BRAF, ALK, and ROS1 were limitedly involved in tumorigenesis and progression of pulmonary LELC." (PMID 34221995, 2021). "Whilst we are not aware of any data that interrogates pathway reactivation upon BRAF inhibition in BRAF mutant lung cancer models, pathway reactivation after KRAS G12C inhibition in G12C mutant lung cancer has been analysed." (PMID 32922659, 2020). "Co-occurrence of mutation in AGTPBP1 and other altered biomarkers EGFR, KRAS, BRAF, ALK and ROS1 in lung cancer was analyzed." (PMID 33276627, 2020). "Genetic mutations in Ki-ras2 Kirsten rat sarcoma viral oncogene homolog (KRAS), epidermal growth factor receptor (EGFR), B-RAF (BRAF), and phosphatidylinositol 3-kinase (PI3K) signaling oncogenic pathways have been identified in lung cancer." (PMID 32984047, 2020). "RAF inhibitors were demonstrated to have the capacity to induce homodimerization of ARAF and heterodimerization of BRAF with CRAF and the scaffolding protein KSR1 in lung cancer cells." (PMID 31652660, 2019). "This is consistent with other studies reporting low TMB in EGFR, ALK, ROS1, or RET-driven lung cancers [30•], but higher in KRAS or BRAF." (PMID 31172347, 2019). "We focused on five important and clinically actionable gene targets (EGFR (Exon 19 deletions, L858, and T790), BRAF (V600), and KRAS (G12/G13)), whose alterations are particularly relevant to lung cancer, melanoma, and colorectal cancer." (PMID 31581267, 2019). "This led to decreased BRAF protein, reduction of downstream MEK and ERK pathway activation and inhibition of growth and differentiation, ultimately leading to death of the lung cancer cells." (PMID 30619326, 2018). "This review concentrates on various lung cancer biomarkers, including EGFR, ALK, and BRAF, as well as their potential mechanisms of drug resistance." (PMID 29973561, 2018). "To prospectively identify mechanisms of resistance to EGFR, ALK, BRAF, and MEK inhibition in lung cancer, we performed CRISPR-Cas9 drug resistance screens in five cancer cell lines with different alterations in the RTK/Ras/MAPK pathway." (PMID 28145866, 2017). "Loss of KEAP1, a negative regulator of NFE2L2/NRF2, modulated the response to BRAF, MEK, EGFR, and ALK inhibition in BRAF-, NRAS-, KRAS-, EGFR-, and ALK-mutant lung cancer cells." (PMID 28145866, 2017). "Thus, ATM mutational status in lung cancer is a mechanistic biomarker for MEK inhibitor response, which may improve patient stratification and extend the applicability of these drugs beyond RAS and BRAF mutant tumours." (PMID 27922010, 2016). "One of our predicted biomarker pairs, a mutation in the BRAF gene and upregulated expression of the PIM1 gene, was experimentally validated to benefit from a therapy combining BRAF inhibitor and PIM1 inhibitor in lung cancer." (PMID 26916442, 2016). "Second, our experimental validation on drug combination of BRAF inhibitor and PIM1 inhibitor was evaluated using two lung cancer cell lines." (PMID 26916442, 2016). "The findings were compared with the clinicopathological features of the lung cancer patients and data from fluorescence in situ hybridization (FISH) performed using BRAF-specific and chromosome 7 centromeric probes." (PMID 25621040, 2015).
lung carcinoma (continued). "Lung cancer is the major cause of cancer-related deaths and many cases of Non Small Cell Lung Cancer (NSCLC), a common type of lung cancer, have frequent genetic/oncogenic activation of EGFR, KRAS, PIK3CA, BRAF, and others that drive tumor growth." (PMID 25466244, 2014). "Four of these markers (BRAF, EGFR, LZTS1, and FGF19) have been directly correlated with lung cancer development and progression." (PMID 25397880, 2014). "We have previously reported that mutations of EGFR, KRAS, BRAF and HER2 were mutually exclusive in 691 resected NSCLC tumors indicating that a single activating mutation in the EGFR-RAS-RAF signaling pathway may be sufficient for the pathogenesis of many lung cancers." (PMID 19238210, 2009). "Additionally, genes involved in the MAPK signaling pathway include BRAF, c-Jun, ERK, JNK, MAP2K1, MAP2K4, MAPK14, and KRAS, which are genes affected by MPs in lung cancer cells." (PMID 41378310, 2025). "While most studies have focused on BRAF and CRAF, the pathological significance of ARAF in lung cancer remains unclear." (PMID 40647542, 2025). "In lung cancer, BRAF V600E typically occurs in never-smokers, with adenocarcinoma histology, and lacks other common driver mutations, resembling other oncogene-driven cancers such as EGFR or anaplastic lymphoma kinase (ALK)-mutated tumors." (PMID 40332392, 2025). "In the present study, we detected and found that there was no T790M mutation or other mutations including BRAF, PIK3CA, HER2 or c-MET amplifications in these resistant lung cancer cells." (PMID 39744423, 2025). "In this case, the NRAS mutation was predominantly identified, the most common gene mutations in lung cancer are all negative, including EGFR, KRAS, BRAF, ALK, ROS1, and so on." (PMID 39507527, 2024). "Notably, our study identified a negative correlation between the expression of key hub genes (AKT, BRAF, GAPDH, KRAS, MYC, and SRC) and immune and stromal cell content in the lung cancer TME." (PMID 39734333, 2024). "For instance, in the lung cancer cohort of the phase II, basket, open-label AcSé trial, an objective response was observed in 43/96 patients in the BRAF V600-mutant group, while no objective response was reached in the BRAF non-V600 arm." (PMID 38539548, 2024). "Here, we present a 10XGenomics scRNA-seq experiment, providing a controlled heterogeneous environment using lung cancer cell lines characterised by the expression of seven different driver genes (EGFR, ALK, MET, ERBB2, KRAS, BRAF, ROS1), leading to partially overlapping functional pathways." (PMID 38307867, 2024). "Interestingly, Cisowski and Bergo (2017) suggested in a mouse lung cancer model that the co-occurrence of two tumor driver genes (KRAS and BRAF) is deleterious, leading to cell cycle exit, senescence, and death." (PMID 36816028, 2023). "Thus, we conducted a correlation study between FGF11 and EGFR (19DEL, L858R), EGFR (Exon 20ins), KRAS (G12C), ALK, ROS1, BRAF, NTRK1/2/3, MET, and RET, which are all recommended by the NCCN guidelines for the diagnosis of nonsmall cell lung cancer." (PMID 37250453, 2023). "The study found that the KRAS gene-driven lung cancer ICI treatment response rate was the highest at 26%, followed by BRAF, with a response rate of 24%, and the MET-driven lung cancer ICI response rate was 16%, which were relatively higher than those of other driver genes." (PMID 35531878, 2022). "Heat shock protein 90 (Hsp90) has been implicated in the assembly of multiple chaperone complexes, regulating the stability and function of client proteins such as wild type c-RAF, mutant BRAF, mutant EGFR, as well as the EML4-ALK fusion protein in lung cancer." (PMID 35326726, 2022). "While somatic mutations of EGFR, BRAF, HER2, MET and chromosomal rearrangements of ALK, ROS1, RET are responsible for lung cancer, risk factors for these genomic alterations have not yet been identified." (PMID 36208308, 2022).
lung carcinoma (continued). "All of the clinically-relevant variants of the EGFR, ALK, BRAF and KRAS genes are unambiguously lung cancer-associated and do not meet CHIP criteria; therefore, the presence of CHIP-associated variants doesn’t affect clinical decision making." (PMID 34031447, 2021). "We also observed a strong negative correlation between PLK1 and FGFR3 in EGFR‐mutant lung cancer cohort, whereas there are no such correlations in BRAF‐mutant lung cancer." (PMID 34369083, 2021). "Similarly, the BRAF gene has been found translocated with TRIM4 in lung cancer and TRIM24 in both melanoma and lung cancer and the FGFR1 gene is translocated with TRIM24 in myeloproliferative syndrome." (PMID 32226386, 2020). "The result was different from the reported effects of ATTM in breast cancer and BRAF-driven papillary thyroid cancer, which suggests that the findings in other cancers should not be simply transplanted to lung cancer." (PMID 32195181, 2020). "Studies in lung cancer have not been reported on the co-occurrence of mutations in PTEN and BRAF, but the PIK3CA mutations have been associated with BRAF mutations." (PMID 32034196, 2020). "The interpretation criteria of BRAF V600E (VE1) IHC in lung cancer have not been established and different criteria were used by different study groups." (PMID 31234388, 2019). "Although BRAF testing was not included in the previous Japan Lung Cancer Society guidelines, it was added in 2018, given that dabrafenib in combination with trametinib has now been established as a standard of care option for NSCLC patients with BRAF mutation." (PMID 31142054, 2019). "Nevertheless, the small proportion of BRAF mutations resulted in negative results (poor prognosis) and provided cognition about mechanisms of acquired resistance to EGFR-TKIs in lung cancer." (PMID 29455669, 2018). "Additionally, BRAF, known as a member of RAS signaling pathway genes, was reported to be involved in pro-mitogenic activity and acquired resistance to EGFR TKIs in lung cancer and colorectal cancer through activating the MAPK signaling axis." (PMID 29455669, 2018). "Next, gene fusion analysis was performed on RNA from FFPE tissue from 169 lung cancers in the prospective 533-sample cohort, which did not harbor mutations in EGFR, KRAS or BRAF (referred to as triple-negative cases hereon)." (PMID 28415793, 2017). "In the first set, we performed three genome scale screens with the MEK inhibitor trametinib, in the NRAS-mutant lung cancer cell line H1299 (NRASQ61K), the BRAF-mutant lung cancer cell line HCC364 (BRAFV600E), and the KRAS-mutant lung cancer cell line CALU1 (KRASG12C)." (PMID 28145866, 2017). "Thus, ATM knockdown sensitized several lung cancer cell lines with different genetic backgrounds to MEK inhibition, and even augmented the response of already sensitive BRAF mutant H1755 cells by an order of magnitude." (PMID 27922010, 2016). "No other examined mutations (EGFR, HER2, HER4, KRAS or BRAF) were found in the lung tumor specimen of the patient, suggesting that HER3-V855Ais the primary driver for the lung cancer pathogenesis." (PMID 26689995, 2016). "The combination of BKM120 with MEK inhibitor Trametinib failed to achieve a reasonable response in RAS- or BRAF-mutant lung cancer patients in a phase Ib trial." (PMID 26544513, 2015). "Given the high prevalence of lung cancer and the availability of targeted therapy, Chinese lung ADC patients without EGFR and KRAS mutations are recommended for HER2 and BRAF mutations detection, especially for those never smokers." (PMID 26102513, 2015). "Oncogenic KRAS binds and activates CRAF more efficiently and mediates KRAS signaling to ERK kinase in lung cancer cells, thus fulfilling an important role as an anti-apoptotic protein independent of BRAF." (PMID 25013473, 2014). "For lung cancers, the genomic panel comprises of ALK, EGFR, KRAS and BRAF." (PMID 23863689, 2013).
lung carcinoma (continued). "Further proving that mutations in the RAS-RAF-MAPK pathway often have one hit per tumor, these tumors had no other known mutations in genes often mutated in lung cancer, such as EGFR, KRAS, HER2, or PIK3CA, or BRAF." (PMID 22928112, 2012). "It is worth mentioning that, although the BRAF biomarker is not currently listed in the catalog for the molecular study of lung cancer, it is included in the indicators, given its clinical relevance and the development of new therapies directed at this molecular target." (PMID 40261489, 2025). "In AKT1 (r = −0.15, p < 0.05), BRAF (r = −0.25, p < 0.05), GAPDH (r = −0.3, p < 0.05), KRAS (r = −0.24, p < 0.05), MYC (r = −0.25, p < 0.05), and SRC (r = −0.24, p < 0.05), stromal score was negatively correlated with lung cancer and the highest correlation coefficient was in GAPDH." (PMID 39734333, 2024). "In this scenario, customized medicine has brought successful outcomes in drug selection for lung cancer patients with NSCLC based on the paradigms of their molecular profiles, specifically those with positive genetic alterations in EGFR, ALK, ROS-1, HER2, BRAF, MET, and RET genes." (PMID 39410578, 2024). "Notably, KRAS, BRAF, ERBB2, PIK3CA, RET, ROS1, ALK, and NRTK1/2/3 have been proposed as prognostic markers, making substantial contributions to genotype-directed therapies for advanced lung cancer." (PMID 36619227, 2023). "However, unlike EGFR or ALK, BRAF has relatively low prevalence in lung cancer, and this study was conducted with untreated patients." (PMID 36076922, 2022). "The identification of target gene alterations is an evolution for the lung cancer management, with the combination of tumor genotyping making personalized treatment possible, and it is of great benefit to patients treated with kinase inhibitors (TKIs) for EGFR, ALK, ROS1, BRAF, or MET." (PMID 35600411, 2022). "Besides EGFR T790M, other resistance mutations can only be detected by the UltraSEEKTM Lung Panel (in BRAF, ERBB2, KRAS and PIK3CA, as well as EGFR C797S) and could be are useful for treatment decision making for lung cancer patients." (PMID 33081150, 2020). "However, there are targeted therapies for PIK3CA and BRAF driver mutations and mutations at PIK3CA or BRAF hotspots were detected in the AEC of six of the 11 lung cancer subjects and none of the non-cancer subjects." (PMID 31711466, 2019). "While overexpression of GIT2 has been described in the literature in breast and lung carcinomas, this fusion with BRAF is novel in tumorigenesis and has not been described in any other type of tumor, hence it is difficult to predict the effect that the deletion will have on the GIT2 gene." (PMID 29141672, 2017). "There is evidence regarding B-RAF inhibition activity in lung cancer, such as that reported in some case reports and proved by interim analysis of a phase II trial, in which patients with BRAF V600E lung cancer beyond first line were treated with dabrafenib and obtained an ORR of 54%." (PMID 27433281, 2016). "In vitro studies confirmed the activation of CRAF/MEK/ERK cascade by the kinase-impaired p.Y472C mutant and demonstrated dasatinib-induced senescence and apoptosis in lung cancer cells expressing kinase-impaired p.G466V mutant, but not in cell lines with kinase-activated BRAF mutants." (PMID 26498038, 2015). "Here, DBA identified candidate rearrangements of RAF1 in lung cancer (DMS-153), pancreatic cancer (PL5), anaplastic astrocytoma (D538-MG), and osteosarcoma (CAL-72), and candidate rearrangements of BRAF in gastric cancer (NCI-N87), breast cancer (HCC38), and glioblastoma (D397-MG)." (PMID 23637631, 2013). "Of these fusions, 16 (including ALK, ARAF, BRAF, FGFR1, FGFR3, RET, and ROS1) and 21 (including ABL1, GNAS, JAK2, and NRG1) were classified as either related to lung cancer, or as oncogenes that have not been reported in lung cancer, respectively." (PMID 36153311, 2022).
lung carcinoma (continued). "“Non-KRAS oncogene-driven lung cancer subtypes (e.g., ROS1, MET, BRAF, HER2, RET) is less well-studied, however, most of these other non-KRAS molecular subtypes (possibly apart from BRAF V600 mutation and MET gene alteration) are associated with a light-to-never smoking history." (PMID 34575691, 2021). "However, despite comparable levels of signalling reactivation, the impressive responses to G12C monotherapy described in lung cancer have not been observed in G12C mutant CRC, a parallel to the disparities in response to BRAF inhibition in CRC." (PMID 32922659, 2020). "Interestingly, SplitFusion detected novel fusions that have not been reported previously in lung cancer, including one squamous cell carcinoma with FGFR3::JAKMP1 fusion, one adenocarcinoma with CLIP2::BRAF fusions (two fusion isoforms in one tumor), and one adenocarcinoma with ITPR2::ETV6 fusion." (PMID 40041857, 2025). "In lung cancer, MEK inhibition was correlated with the activation of EGFR and stimulation of its specific RTK (receptor tyrosine kinases) receptor that has the further capacity to induce a transient inhibition of ERK phosphorylation in BRAF non-V600E, but not BRAF V600E, mutant cells." (PMID 31652660, 2019).